BCL2 (BCL2 apoptosis regulator)
Diseases named in the same sentence as BCL2 in open-access papers (continued):
Sharing a sentence is not in itself a finding about the gene and the disease.
multiple myeloma (continued). "This review analyzes new data on venetoclax in AL amyloidosis and PCL and highlights the increasing significance of BCL-2 inhibition in plasma cell neoplasms beyond MM." (PMID 40190562, 2025). "In conclusion, prospective trials are needed to corroborate the favorable outcomes observed, since the information on the efficacy of BCL-2 inhibitors in PCL and AL amyloidosis is based on small cohorts or case reports." (PMID 40190562, 2025). "A detailed cross-comparison with other myeloma models showed pronounced parallels, most notably with the model induced by KRASG12D in conjunction with BCL2 overexpression, which exhibited the highest similarity (p = 1.8 × 10−246; odds ratio (OR) = 3.7)." (PMID 39198400, 2024). "DT2216 sensitive myeloma cells expressed the highest levels of BCLXL and moderate levels of either BCL2, MCL1 or both." (PMID 37534243, 2023). "These miRNAs were downregulated, and BCL2, BCL2L1, and MCL1 genes were upregulated in samples from AL amyloidosis patients compared with MM and HC samples." (PMID 36694297, 2023). "The expression of miR‐9‐5p, miR‐181a‐5p, BCL2, MCL1, and BCL2L1 in AL amyloidosis and MM patients was analyzed by t(11:14) status (which was determined by fluorescence in situ hybridization [FISH])." (PMID 36694297, 2023). "ABT-199 is effective in hematopoietic malignancies: Multiple Myeloma (MM) and acute and chronic myeloid leukemia (AML and CML) overexpressing BCL-2." (PMID 35443750, 2022). "Gene expression analyses have identified that BCL2 is frequently upregulated in Waldenstrom macroglobulinemia, a transcriptional profile more closely resembling CLL than multiple myeloma." (PMID 35659041, 2022). "It is showed that LINC00461 is elevated in multiple myeloma, and LINC00461 promotes the expression of Bcl-2 protein by targeting miR-15a/miR-16, thereby inhibiting cell apoptosis." (PMID 35783530, 2022). "Mechanistically, venetoclax induces myeloma cell apoptosis by displacing proapoptotic BH3-only proteins (e.g., BIM and PUMA) from BCL2, leading to caspase-dependent cell death." (PMID 35799216, 2022). "For example, in myeloma cells, it activates the MAPK, PI3K⁄AKT, and NF-κB pathways, which leads to an up-regulation of Mcl-1 and Bcl-2 anti-apoptotic proteins." (PMID 35144648, 2022). "Inflammatory cytokines such as IL-6, derived from bone marrow (BM), mediate BCL2, BCLXL, and MCL1 expression in MM, forming complex network interactions between the marrow stroma and myeloma cells." (PMID 35982976, 2022). "Here we show that the clonal plasma cells in AL amyloidosis are highly primed to undergo apoptosis and dependent on pro-survival proteins MCL-1 and BCL-2." (PMID 36184661, 2022). "MicroRNAs miR-193b-3p and miR-21-5p emerged among the top deregulated miRNAs in myeloma cells when directly co-cultured with pMSCs, and we show their contribution to changes in MCL-1 and BCL-2 protein expression and in the activity of S63845 and venetoclax." (PMID 33806619, 2021). "We show that co‐operative targeting of BCL‐2 and MCL‐1 with venetoclax and S63845, induces a synergistic apoptotic response, in human myeloma cell lines (HMCL) and primary samples." (PMID 35846088, 2021). "The rate of apoptosis inthe myeloma cells after BTZ treatment considerably increased, which indicated an increase in the mRNA of SOCS3, PTEN, BCL-2, and CDKN1." (PMID 34837676, 2021). "The anti‐apoptotic proteins B‐cell lymphoma‐2 (BCL‐2) and myeloid cell leukaemia‐1 (MCL‐1), are necessary for MM survival, although most myelomas are more dependent on MCL‐1." (PMID 35846088, 2021). "Abbvie, who has a long tradition in BCL-2 inhibiting compounds, is testing ABBV-467 in monotherapy for multiple myeloma patients." (PMID 33308268, 2020). "We determined the sensitivity to BCL2 and MCL1 inhibitors of 60 consecutive myeloma samples (23 at diagnosis and 37 at relapse) with a percentage of plasma cells of at least 3%." (PMID 32371863, 2020).
multiple myeloma (continued). "The analysis of the whole transcriptome data revealed different expression levels of several genes, such as JAK1, JAK2, JAK3, RAF, IL6R, NCAM (CD56), WHSC1, MCL1, BCL2, and IGF1, which showed myeloma pathogenesis." (PMID 30079703, 2019). "A series of previous studies showed that miR-16 enhanced cell apoptosis by targeting the oncogene Bcl2 in hepatic stellate cells, and miR-16 acted as putative tumor suppressor by targeting VEGF-A in multiple myeloma." (PMID 29255591, 2017). "In multiple myeloma cells, FTY720-induced ROS activity promotes autophagy, reduces the expression of Mcl-1, Survivin, Bcl-2 and increases cleavage of Bid, ultimately leading to apoptosis of multiple myeloma cells." (PMID 29234668, 2017). "We identified STAT3 and MEK/ERK/BCL2 as CKS1B-downstream signaling pathways; and thereby provided targets for the development of new therapeutic approaches for CKS1B over-expressing myeloma and other tumor malignancies." (PMID 20930946, 2010). "Importantly, among the upregulated genes, there were several genes encoding established pro-survival and anti-apoptotic factors in myeloma, including MYC, IRF4, NFKB1/2, BCL2, and BCL2L1." (PMID 38911853, 2024). "Bone marrow mesenchymal stem cells derived exosomal miR-483 increased multiple myeloma’s malignant progression by inhibiting TIMP2 expression, and the inhibition of miR483 increased expression of p21 and downregulated the expression of c-Myc and Bcl-2." (PMID 36980601, 2023). "Additionally, the combination of glucocorticoids with inhibitors of Bcl-2 or MCL-1 such as venetoclax and bortezomib, respectively, has been shown to be a promising and safe treatment for relapsed/refractory multiple myeloma." (PMID 36539401, 2022). "The absence of stable downregulation of the BCL2 mRNA has suggested that the double heptamer-type sgRNA targets other cellular RNAs to reduce the myeloma cell viability." (PMID 35628198, 2022). "Knockdown of SNHG16 in multiple myeloma cells suppressed cell proliferation, induced cell arrest and promoted the apoptosis via inducing cleaved-Caspase-3, cleaved-Caspase-9, Foxa3a and Bax expression, while inhibiting CCND1, Bcl-2, Cyclin D1, PI3K and p-AKT." (PMID 35740344, 2022). "The ratio of BCL2, BCL-XL and MCL1 expression in myeloma cell lines, primary cells and patient samples in clinical trials has been associated with venetoclax sensitivity, suggesting variable relative dependencies on these pro-survival proteins as a driver of intrinsic resistance." (PMID 35659041, 2022). "In parallel, by examining 5′-half-tRNA-type and 14-nt linear-type sgRNAs designed to target appropriate mRNAs such as the BCL2, CCND1, and IRF4 mRNAs for their ability to induce apoptosis in myeloma cells, potential sgRNA therapeutics would be expected to be found." (PMID 35628198, 2022). "Based on our results, highly primed clonal plasma cells from patients with AL amyloidosis would be sensitive to single agent treatment with a proteasome inhibitor, dexamethasone, or an inhibitor of MCL-1 or BCL-2, especially, when treatments are assigned with biomarkers such as BH3 profiling." (PMID 36184661, 2022). "In results from in vitro chemosensitivity as well as BH3 profiling assays, which have both been previously shown to predict patient responses to BH3 mimetics, we consistently found that clonal plasma cells in AL amyloidosis can be highly dependent on MCL-1, or BCL-2 for survival, or both." (PMID 36184661, 2022). "Moreover, with the identification of novel targets, new drug classes have entered the myeloma armamentarium, such as XPO1 inhibitors (selinexor), HDAC inhibitors (panobinostat), and anti-BCL-2 agents (venetoclax)." (PMID 34680358, 2021).
multiple myeloma (continued). "Similar to myeloma cells, BCL-2 overexpression in AML is heterogeneous, and not always present, but there is evidence to support apoptosis dysregulation." (PMID 34073976, 2021). "On the other hand, in myeloma cells, the binding of BIM to BCL-XL and BCL-2, but not the expression pattern, is associated with sensitivity to ABT-737 (BCL-2/BCL-XL/BCL-W inhibitor)." (PMID 35008216, 2021). "In multiple myeloma cell lines, BetA activates protein phosphatase 2A (PP2A), which regulates apoptosis and autophagy-mediated cell death according to different levels of BCL-2 expression." (PMID 33233671, 2020). "Because the use of BCL2 and MCL1 inhibitor combination could also increase toxicities, we paid attention to evaluate suboptimal doses of each inhibitor in myeloma cells." (PMID 32371863, 2020). "Interestingly, in vitro studies in myeloma cell lines demonstrated the synergistic effect of venetoclax in combination with dexamethasone, via the increased expression of BIM and BCL-2, promoting BCL-2 dependence." (PMID 32183335, 2020). "Bcl2 and IAP families are anti-apoptotic proteins deregulated in multiple myeloma (MM) cells." (PMID 27494845, 2016). "Myeloma cell lines particularly dependent on Bcl-2 for survival are sensitive to ABT-199, whereas cell lines dependent or co-dependent on other Bcl-2 family proteins are less sensitive to Bcl-2 inhibitors." (PMID 27363832, 2016). "As we found that STAT1C-induced apoptosis in ESCC correlates with the down-regulation of several pro-survival proteins such as BCL-2 and BCL-xL, previous studies also have shown that STAT1 can promote apoptosis by down-regulating BCL-2 and BCL-xL in multiple myelomas." (PMID 25355139, 2014). "Thus, our findings clarify the SKP2/ p27Kip1-independent mechanisms of CKS1B activity in maintaining myeloma cell growth and survival, and also provide a rationale for specifically targeting STAT3 and MEK/ERK/BCL2 in aggressive CKS1B-overexpressing MM." (PMID 20930946, 2010). "Western blots detected increased levels of p-STAT3, p-MEK1/2 and p-ERK1/2 in p27Kip1-transfected myeloma cells with no remarkable effect on p-BCL2 levels compared with WT and EV controls." (PMID 20930946, 2010). "Interestingly, we found that Bik expression is directly correlated to Bcl-2 protein expression in both HMCL (P=0.0006) and primary myeloma cells (P=0.0005)." (PMID 21063407, 2010). "Thus, it is reasonable to conclude that CKS1B mediates myeloma cell growth and drug-resistance through activation of STAT3 and MEK/ERK/BCL2 signaling pathways." (PMID 20930946, 2010). "The BCL2/MCL1 ratio was not affected by t(11:14) in either AL amyloidosis or MM." (PMID 36694297, 2023). "Many myeloma mouse genetically engineered models have focused on the dysregulation (overexpression or knock-out) of a particular gene or pathway, most notably, the dysregulation of MYC or BCL2, as well as the earlier spontaneous 5T models that have M spikes and develop bone lesions." (PMID 32923678, 2020). "Unlike BCL-2, which is lowly expressed in multiple myeloma (MM), levels of BCL-X are much higher and may therefore be a critical survival factor for MM." (PMID 30671383, 2018). "In contrast, other groups have shown that Bcl-2-transfected 8226 and ARP-1 myeloma cells still remained sensitive to TRAIL and that Bcl-2 failed to block cytochrome c release after exposure to TRAIL." (PMID 12644829, 2003). "The present study aimed to determine whether the combination of BCL2 inhibitor venetoclax and MCL1 inhibitor S63845 at low doses could be of benefit for myeloma cells beyond the single selective inhibition of BCL2 or MCL1, especially for myeloma cells not dependent on BCL2 or MCL1." (PMID 32371863, 2020).
neuroblastoma (219 papers, 2002 to 2025). Neuroblastoma (NB) is the most common solid, extracranial childhood tumor. "BCL-2 expression in neuroblastoma is associated with drug resistance, unfavourable histology and N-MYC amplification, and a high-risk phenotype." (PMID 35568716, 2022). "Further, siRNA targeting of Bcl-2 in neuroblastoma causes a high level of cell apoptosis and a significant suppression of tumor growth." (PMID 29686263, 2018). "Previous studies also demonstrated that high-risk neuroblastoma cell lines derived from human tumors with the poorest prognosis are dependent on Bcl-2 for survival." (PMID 29686263, 2018). "Taken together, these results suggested that the reduced expression of Bax and cleaved caspase-3 and increased production of Bcl-2 in neuroblastoma cells were the mechanisms underlying the protective effect of AITC against LPS-induced neuronal death." (PMID 28671636, 2017). "ABT199 caused apoptosis more potently in neuroblastoma cell lines expressing high BCL-2 and BIM/BCL-2 complex levels than low expressing cell lines." (PMID 27056887, 2016). "Together, these findings confirm that ABT199 causes apoptosis in BCL-2-dependent neuroblastoma cells via activation of the intrinsic apoptotic pathway." (PMID 27056887, 2016). "This combination therapy caused marked downregulation of N-Myc, Bcl-2, and neural cell adhesion molecule with induction of differentiation in neuroblastoma." (PMID 21876694, 2012). "In neuroblastoma bcl-2 expression seems to correlate with the morphology and differentiation of neuroblastoma cells in vitro, greater bcl-2 expression being associated with more neuroblastic cells." (PMID 12085183, 2002). "CNP-Cur and Dex-CNP-Cur formulations cause neuroblastomas to produce more ROS and a significantly lower ratio of Bcl-2/Bax (Bax is an apoptosis-inducing gene and Bcl-2 stands for anti-apoptic factors), which leads to the release of cytochrome C and the activation of caspase 3/7 and apoptosis." (PMID 37507944, 2023). "One potential targeted treatment avenue for high-risk neuroblastoma may involve the induction of apoptosis by selective inhibition of the anti-apoptotic B-cell lymphoma 2 (BCL2) proteins." (PMID 37723317, 2023). "Resveratrol caused neuroblastoma cell cytotoxicity with S-phase arrest, decreased clonal expansion, and increased mitochondria-mediated intrinsic caspase-dependent apoptosis by selectively targeting cyclin D1, Bcl-2, Bcl-xL, and Mcl-1 proteins." (PMID 38249515, 2023). "Functional analysis in the cell line model (SH-SY5Y neuroblastoma cell line) revealed that CAG repeats of pathogenic expansion in the C-terminus of the CACNA1A gene probably lead to activation of apoptosis factors (Bcl-2/Bax, caspase, and PARP) and induce cell apoptosis in nerve cells." (PMID 34727962, 2021). "In neuroblastoma cells, an increase in ROS caused by venom of snake therapy increased pro-apoptotic proteins such as Bax, and there was a down-regulation of anti-apoptotic Bcl-2 protein after venom treatment." (PMID 34834153, 2021). "The intrinsic apoptotic pathway represents an attractive therapeutic target, as neuroblastomas frequently evade apoptosis through increased expression of the anti-apoptotic protein Bcl-2." (PMID 40804038, 2025). "The results showed that the combination was highly synergistic in neuroblastoma cell lines and patient-derived xenografts with high BCL-2 expression, significantly improving event-free survival in mice." (PMID 40332322, 2025). "CS induced apoptosis in SH-SY5Y neuroblastoma cells via the mitochondrial apoptotic pathway by increasing Bax and reducing Bcl-2 expression." (PMID 41346617, 2025). "BCL2 inhibitors have shown promise in preclinical neuroblastoma models, particularly in combination with MEK inhibitors." (PMID 40854877, 2025). "Co-expression of MYCN and Bcl-2 genes has also been shown to induce the secretion and activation of matrix metalloproteinases in neuroblastoma, leading to the degradation of the extracellular matrix." (PMID 38959634, 2024).
neuroblastoma (continued). "The combination of RA with navitoclax disrupted the binding of BIM to BCL-XL in MBG3 and to BCL-2 in neuroblastoma, inducing apoptosis in vitro and in vivo." (PMID 38942989, 2024). "OXY induces autophagy along with apoptosis in neuroblastoma cells, down-regulates the anti-apoptotic Bcl-2, and up-regulates the pro-apoptotic Bax protein." (PMID 39065570, 2024). "In neuroblastoma, studies have shown that genistein downregulates survival proteins (e.g., BCL2) and induces death factors and death domains (e.g., TNFR-1, TRADD, FADD)." (PMID 38249515, 2023). "Consistent with our observation in the therapeutic sensitivity analysis, high-NE-score cell lines from both SCLC and neuroblastoma were more sensitive to BCL2 depletion." (PMID 37255415, 2023). "We utilised cisplatin-adapted neuroblastoma cell lines as well as patient tissues before and after relapse to study alterations of BCL2 proteins upon chemoresistance." (PMID 37723317, 2023). "Resveratrol administration, in conjunction with arsenic trioxide, has yielded benefits in neuroblastoma management, by regulating cellular viability and apoptosis, brought about by reduced levels of caspase-3 and caspase-9, as well as Bcl-2." (PMID 36672729, 2023). "By contrast, cells of other cell lines such as SH-SY5Y (human neuroblastoma) had very low levels of the SAV1 protein but very high protein levels of BCL-2." (PMID 38136317, 2023). "In line with this reasoning, activation of the ISR by thapsigargin was also sufficient to downregulate c-MYC, HIF-1α, and MCL-1 in neuroblastoma cells already within 1 h of treatment, whereas BCL-2 levels remained unchanged." (PMID 37973789, 2023). "Salvigenin, a known polyphenol flavonoid, also shown to be present in BLS WIE, inhibits hydrogen peroxide-induced apoptosis, reduces the generation of ROS and reduces caspase-3 levels as well as Bax/Bcl-2 ratio in SH-Sy5Y neuroblastoma cells." (PMID 37818190, 2023). "Among the very few vulnerabilities selected from both SCLC and neuroblastoma, we identified BCL2, a well-characterized gene in both cancer types." (PMID 37255415, 2023). "In neuroblastoma, butein treatment resulted in a significant ROS increase and cell cycle arrest, regulated the Bcl-2/Bax ratio, stimulated caspase and PARP activity, decreased cell viability, and induced apoptosis." (PMID 38249515, 2023). "Venetoclax has previously shown to be active in neuroblastoma cells with high BCL-2 expression and high BIM/BCL-2 complex levels." (PMID 36895472, 2023). "Next, we tested the expression of NTRK2 (neurotrophic receptor tyrosine kinase 2, TrkB) and BCL2 (B cell CLL/lymphoma 2); both genes linked to neural differentiation whose expression is increased in RA-treated neuroblastoma cells." (PMID 35831557, 2022). "Se supplementation triggers the phosphorylation of Bcl-2 and apoptosis of neuroblastoma cells under hypoxia." (PMID 36547898, 2022). "Currently, Bcl-2 inhibitors in combination with classical cytostatic drugs are being investigated in clinical trials for the treatment of relapsed or refractory neuroblastoma." (PMID 35884854, 2022). "Results with ABT-263 also suggested that ABT-263 mediates its effects in neuroblastoma through BCL-2 inhibition." (PMID 35568716, 2022).